SMAD3 (SMAD family member 3)
Diseases named in the same sentence as SMAD3 in open-access papers (continued):
Sharing a sentence is not in itself a finding about the gene and the disease.
hip osteoarthritis (2 papers, 2018 to 2025). "Fine mapping implicated SMAD3 and PLEC as candidate genes that may be involved in the development of hip shape and hip osteoarthritis." (PMID 39574169, 2025). "Rs12901499, within the SMAD3 locus, was positively associated with HSM4 (β 0.05, P 1.69 × 10−13), describing greater acetabular coverage and narrower femoral neck, and was also found to be protective of hip osteoarthritis (β −0.07, P 2.83 × 10−15)." (PMID 39574169, 2025). "In terms of specific genes likely to affect both hip shape and either hip osteoarthritis or fracture, SMAD3 and PLEC were the only genes identified through colocalisation between GWAS signals and mRNA expression in human joint tissue and both were associated with hip osteoarthritis." (PMID 39574169, 2025). "In addition, the HSM4 and hip osteoarthritis GWAS signals around rs12901499 colocalised with each other (PP 99%) and the HSM4 GWAS signal colocalised with SMAD3 mRNA expression in both healthy and degraded human cartilage (PP 98% in both tissues)." (PMID 39574169, 2025). "SMAD3 is an important member of the TGF-β pathway which plays an important role in chondrogenesis and has previously been implicated in hip osteoarthritis but was not known to be associated with hip shape." (PMID 39574169, 2025).
hyperlipidaemia (2 papers, 2021 to 2023). "Therefore, to investigate whether the activation of SIRT1 could attenuate hyperlipidemia-induced cardiac fibrosis in vivo and whether the TGF-β/Smad pathway is involved in this process, Masson’s trichrome staining and collagen III, TGF-β, and Smad3 expression were assessed." (PMID 37277452, 2023).
Infertility (2 papers, 2022 to 2024). "With this context, the identification of VDR, NCOR1, and SMAD3 in this study must be evaluated further to explore their role in therapies for VD-deficient females with infertility." (PMID 38586664, 2024). "Since SMAD3 is involved in endometrial receptivity and embryo implantation, these findings suggest SMAD3 as a key protein in adenomyosis-related infertility." (PMID 35207707, 2022).
influenza (2 papers, 2019 to 2025). An acute viral infection of the respiratory tract, occurring in isolated cases, in epidemics, or in pandemics; it is caused by serologically different strains of viruses (influenzaviruses) designated A, B, and C, has a 3-day incubation period, and usually lasts for 3 to 10 days. "Third, clinical samples from patients infected with the influenza virus were not examined, and the involvement of the TGF-β/Smad3 signaling pathway in influenza-induced PF remains unexplored." (PMID 41011177, 2025).
intrahepatic cholangiocarcinoma (2 papers, 2023 to 2025). A carcinoma that arises from the intrahepatic bile duct epithelium in any site of the intrahepatic biliary tree. "In intrahepatic cholangiocarcinoma (ICC), in vitro assays confirmed its ability to suppress cell proliferation and inhibit epithelial–mesenchymal transition (EMT) through modulation of the HIF-1α-mediated TGF-β1/p-Smad3 signaling pathway." (PMID 41154606, 2025).
juvenile polyposis (2 papers, 2022 to 2023). "Although juvenile polyposis patients have been screened for SMAD2 and SMAD3 mutations, only SMAD4 germline mutants are identified as an underlying cause of juvenile polyposis." (PMID 36267157, 2022).
Kawasaki disease (2 papers, 2012 to 2022). A rare inflammatory disease characterized by an acute febrile, systemic, self-limiting, medium-vessel vasculitis primarily affecting children. "Furthermore, Kawasaki disease and secondary coronary artery lesions are found to be associated with ADAM17 genetic variants through TGF-β/Smad3 signaling pathway." (PMID 36313337, 2022).
kidney inflammation (2 papers, 2021 to 2023). "Similar to these findings, our results show that SMAD3 deficiency can protect against antibody-induced nephritis in mice, adding to the growing attractiveness of this signaling axis as a therapeutic target in nephritis." (PMID 33669690, 2021). "Moreover, mice deficient in Smad3 were protected from anti-GBM disease, indicating that the more severe nephritis and fibrotic disease observed in the 129sv strain of mice were regulated by SMAD3." (PMID 33669690, 2021). "Mice with Smad3 gene deficiency were used to determine whether the enhanced anti-GBM nephritis in 129sv mice is SMAD3 dependent." (PMID 33669690, 2021). "Collectively, these findings indicate that the heightened experimental nephritis and fibrotic disease in the 129sv strain of mice are regulated by SMAD3, which could be a potential therapeutic target for immune-mediated nephritis." (PMID 33669690, 2021). "Whether the contribution of TGF-β to the pathogenesis of nephritis is SMAD3 dependent and whether the enhanced anti-GBM nephritis in 129sv mice is driven by SMAD3 are currently unknown." (PMID 33669690, 2021). "Our findings, as well as those of previous reports, support a critical role for TGF-β/SMAD signaling in the pathogenesis of renal disease and that targeting SMAD3 appears to be an attractive therapeutic option for immune-mediated nephritis, including lupus nephritis and anti-GBM nephritis." (PMID 33669690, 2021).
latent infection (2 papers, 2021). "An inability to downregulate SMAD3 during latent infection results in a loss of viral genomes from the infected cells and whether this phenotype is due to enhanced IFN signaling remains to be determined." (PMID 34411201, 2021). "We have previously identified SMAD3 as a target of the HCMV miRNAs miR-UL22A-5p and -3p, and have shown that miR-UL22A-mediated reduction of SMAD3 is required for genome maintenance during latent infection." (PMID 34411201, 2021).
lung squamous cell carcinoma (2 papers, 2023 to 2024). "The TGF-β1 transcription factor SMAD3 is epigenetically repressed in tumour-associated fibroblasts (TAFs) from lung squamous cell carcinoma (SCC) but not adenocarcinoma (ADC) patients, which elicits a compensatory increase in SMAD2 that renders SCC-TAFs less fibrotic." (PMID 36572730, 2023).
malignant glioma (2 papers, 2015 to 2023). A grade III or grade IV glioma arising from the central nervous system. "In conclusion, the present study provided evidence that the Smad3 pathway is important in malignant glioma cells and suggested that Smad2 and Smad3 have tumor suppressor activities." (PMID 25891822, 2015). "Considering these results, the preset study hypothesized that the ability to resist TGFβ2-mediated growth inhibition in malignant glioma cells was due to a decrease in the expression levels of Smad2 and Smad3 in the TGFβ2 signaling pathway." (PMID 25891822, 2015). "Taken together, the JICD1/SMAD3-TWIST1-MMP2 and MMP9 axes regulate the aggressive behavior of malignant gliomas." (PMID 38092725, 2023).
membranous nephropathy (2 papers, 2022 to 2023). "However, Klotho expression was inhibited and Smad3 signaling was activated in human kidney biopsies from CKD patients with membranous nephropathy (MN)." (PMID 35064106, 2022).
meningioma (2 papers, 2005 to 2022). A generally slow growing tumor attached to the dura mater. "The western blotting of cytoplasmic and nuclear proteins revealed increased nuclear translocation of Smad2 and Smad3 in meningioma cells cocultured with M2-MDEs." (PMID 35637794, 2022). "Recent studies have suggested and demonstrated that TGF-β directly acts with Smad3 to regulate the sensitivity to TGF-β induced apoptosis and another study showed that TGF-β exerts a largely inhibitory effect on basal meningioma proliferation possibly through Smad 2/3." (PMID 15927076, 2005).
myelofibrosis (2 papers, 2022). A partial or complete replacement of the bone marrow stroma by fibrous tissue. "Whether the loss of SMAD3 activity contributes to suppression of myelofibrosis after JNK inhibitor treatment will require further study." (PMID 35439167, 2022). "Combined JAK1/2 and SMAD3 treatment proved to be the most efficient in preventing the myelofibrosis induced by BM-MSCs via neoplastic MPN mononuclear cells regardless of the presence of JAK2 mutation." (PMID 35288649, 2022).
myeloma (2 papers, 2017 to 2018). "However, the precise biological role of SMAD3 in IMiD resistance in myeloma and its potential use as a biomarker of responsiveness to IMiDs require further investigation." (PMID 29130642, 2018).
myopia (2 papers, 2022). "On the one hand, the results of Metascape revealed a potential role of TF in the development of myopia with the enrichment of Smad6, NrOb2, Gtf2i, Tfap2a, Pax7, Pax6, Sox9 and Smad3." (PMID 34841657, 2022). "Enrichment analysis revealed top eight transcription factors, including PAX6 and Smad3, related to myopia." (PMID 34841657, 2022).
ocular hypertension (2 papers, 2020 to 2022). Abnormally high intraocular pressure. "In terms of the molecular mechanisms of steroid-induced ocular hypertension, a recent study showed that Smad3 deficiency resulted in complete inhibition of steroid-induced ocular hypertension in mouse eyes." (PMID 35055036, 2022). "Given the relevance of Smad-dependent TGFβ2 pathways in ocular hypertension and glaucoma, we performed Western blotting to investigate the expression of total and phosphorylated Smad2 and Smad3 molecules." (PMID 32973273, 2020).
Osteopenia (2 papers, 2019 to 2021). Osteopenia is a term to define bone density that is not normal but also not as low as osteoporosis. "A study on mice revealed their essential role in bone formation, as SMAD3 knockout resulted in osteopenia." (PMID 34066823, 2021).
ovarian dysfunction (2 papers, 2022). The inability of the ovaries to function. "In mice, Smad3 deletion causes mammary development abnormalities secondary to ovarian insufficiency." (PMID 36313568, 2022).
ovarian tumor (2 papers, 2010 to 2021). "Because activins signal through SMAD2 and SMAD3 in vitro and loss of SMAD3 attenuates ovarian tumor development in inhibin-deficient females, we sought to determine the role of SMAD2 in the development of ovarian tumors originating from the granulosa cell lineage." (PMID 20565978, 2010). "On the other hand, loss of SMAD3 in the Inha null mice attenuates but does not prevent ovarian tumor development, suggesting that SMAD2 may partially compensate for the loss of SMAD3." (PMID 20565978, 2010). "In the case of conditional deletion of Smad2, SMAD3 compensates for the deficiency of SMAD2 and transduces essential signals contributing to ovarian tumor development; consequently, tumorigenesis is not altered." (PMID 20565978, 2010). "To dissect the activin downstream signaling components during ovarian tumorigenesis, we previously generated Inha/Smad3 double knockout mice in which females are substantially, but not completely, protected from the development of ovarian tumors and the accompanying cachexia syndrome." (PMID 20565978, 2010). "Since deletion of SMAD3 only delays ovarian tumor development in the Inha null mice, we were interested in determining the potential involvement of SMAD2 in mediating the potentiated activin signaling in ovarian tumors lacking inhibins." (PMID 20565978, 2010).
pancreatitis (2 papers, 2022 to 2024). Inflammation of the pancreas. "In our study, we found out that VARs on SMAD3 were significantly linked to the development of pancreatitis: 33% of patients with SMAD3 variants suffered from pancreatitis while the incidence of pancreatitis in the complete cohort was only 14%." (PMID 35053465, 2022). "VARs on SMAD3 were significantly linked to the development of pancreatitis (p = 0.034)." (PMID 35053465, 2022).
pituitary tumor (2 papers, 2020 to 2024). A benign or malignant neoplasm affecting the pituitary gland. "Menin interacts with the TGFβ-regulated transcription factor Smad3 in rat pituitary tumor cells, promoting the activation of TGFβ target genes that inhibit cell growth." (PMID 39336822, 2024). "LncRNA SNHG1 activated the TGFBR2/SMAD3 and RAB11A/Wnt/β-catenin pathways to promote the progression of pituitary tumors by sponging miR-302/372/373/520 in pituitary tumor cells." (PMID 32192168, 2020).
Raynaud syndrome (2 papers, 2014 to 2025). "It is worth noting that the two patients with SSc-ILD, with altered variants in the SMAD3 gene, have a vascular component in the clinical picture: vascular damage, Raynaud’s syndrome." (PMID 40843700, 2025). "Finally, Raynaud syndrome or acrocyanosis were observed in half of the SMAD3 mutation carriers (significantly more frequently than in normal subjects or Marfan controls), suggesting also microvasculature involvement." (PMID 24804794, 2014).
Renal atrophy (2 papers, 2018 to 2020). Atrophy of the kidney. "Indeed, using the TRPM7 inhibitor NS8593 suppressed TRPM7 expression and cell proliferation both in tubular epithelial cells and interstitial cells, prevented upregulation of Smad2/Smad3 signaling, and attenuated renal atrophy and fibrosis." (PMID 32047249, 2020). "Similarly, the STK of mice with deficiency of Smad3, a critical intermediate of TGF-β signaling, was protected from development of renal atrophy, interstitial fibrosis, and tubular atrophy." (PMID 29872089, 2018).
Right ventricular hypertrophy (2 papers, 2021 to 2025). In this case the right ventricle is more muscular than normal, causing a characteristic boot-shaped (coeur-en-sabot) appearance as seen on anterior- posterior chest x-rays. "Additionally, Luo confirmed that miR-29a-3p, regulated by HIF-1α and SMAD family member 3 (Smad3), could significantly improve HPH and right ventricular hypertrophy." (PMID 39979525, 2025).
sarcoma (2 papers, 2019 to 2024). A usually aggressive malignant neoplasm of the soft tissue or bone. "Activation of SMAD3 and AKT, which is triggered by TGFβ signaling to induce collagen expression, was also inhibited by IFNγ in these tumor cells, suggesting that abundant IFNγ reduces TGFβ-mediated collagen expression in sarcoma cells." (PMID 39574893, 2024).
skin aging (2 papers, 2022 to 2024). The gradual irreversible changes in structure of skin that occur as a result of the passage of time.. "In general, SBP can promote the synthesis of Col I and tropoelastin by increasing TGF‐β1 and Smad3 in the skin of aging model mice to delay skin aging." (PMID 38370085, 2024). "Higenamine enhances collagen production in the skin through TGF-β/Smad3 signaling and potentially suppresses UVB-induced skin aging." (PMID 35529934, 2022).
Skin ulcer (2 papers, 2021 to 2023). A discontinuity of the skin exhibiting complete loss of the epidermis and often portions of the dermis and even subcutaneous fat. "STAT3 regulates the cellular stress response, as well as apoptosis and wound-healing pathways while Smad3 induces the expression of alpha-SMA, VEGF, and TGF-β1 in dermal fibroblasts and induces an increased chemotactic response, accelerating tissue repair in skin ulcers." (PMID 37269014, 2023).
small cell lung carcinoma (2 papers, 2021 to 2025). Small cell lung cancer (SCLC) is a highly aggressive malignant neoplasm, accounting for 10-15% of lung cancer cases, characterized byrapid growth, and early metastasis. "Finally, we show that SMAD3, ZNF217, KLF13, GATA2, GATA3, KLF7, and PHOX2B are components of CRCs in other cancers, including DLBCL, pancreatic, gastric, breast, and small cell lung cancer." (PMID 35201514, 2021).
abortion (1 paper, 2017). the ending of pregnancy by removing a fetus or embryo before it can survive outside the uterus. "Collectively, the findings suggested that ESA restricted Foxp3 expression by inhibiting TGFßRII/Smad2/Smad3/Smad4 signalling, ultimately resulting in abortion." (PMID 28300338, 2017).
acne (1 paper, 2024). An inflammatory process of the sebaceous glands which is characterized by comedones, nodules, papules and/or pustules on the skin. "Based on the results of research, IGF-1 related to insulin and a specific inhibitor of Smad3, and IL-17 antibodies related to inflammatory pathways, are expected to become targets for the prevention and treatment of acne-induced PSs, providing potential directions for new drug development." (PMID 38585341, 2024). "Some studies have shown that a specific inhibitor of Smad3 can improve fibrosis and inflammation by inhibiting the TGF-β/Smad3 signaling pathway, but this has not been observed in studies of acne-induced PSs." (PMID 38585341, 2024).
acute liver failure (1 paper, 2019). Rapid deterioration of liver function causing encephalopathy and coagulopathy. "Furthermore, we have previously demonstrated that TGFβR2 expression is found predominantly in neurons in the brain and that TGFβ signaling increases the activation of SMAD3 in neurons during acute liver failure." (PMID 30940161, 2019).
acute pancreatitis (1 paper, 2014). An acute inflammatory process that leads to necrosis of the pancreatic parenchyma. "High levels of Smad3 were observed in bronchial epithelium, vascular endothelium, infiltrating, and fibroblast-like cells, while low levels were detected in alveolar cells in both sham controls and with acute pancreatitis induction." (PMID 24688224, 2014).
Airway obstruction (1 paper, 2023). Obstruction of conducting airways of the lung. "We observed that there is 1 SNP (rs56375023, located in SMAD3) that was related to three associated traits: blood eosinophil counts, airway obstruction and atopy." (PMID 37186423, 2023). "TGF‐ß also plays a role in airway remodelling and structural cell proliferation via Smad3 which leads to airway obstruction and AHR." (PMID 37186423, 2023).
allergic asthma (1 paper, 2024). A asthma with a basis in a pathological type I hypersensitivity reaction. "We establish that scutellarin effectively improves the allergic asthma conditions by regulating the Smad2/Smad3 and MAPK pathways." (PMID 38168709, 2024).
allergic contact dermatitis (1 paper, 2024). An inflammatory skin condition caused by an immune response to direct contact between the skin and an allergen. "However, IL-37 was found to be responsible for the anti-allergic contact dermatitis by regulation of Smad3 participation." (PMID 39065733, 2024).
allergic rhinitis (1 paper, 2024). Inflammation of the nasal mucous membranes caused by an IgE-mediated response to external allergens. "Furthermore, the MCODE plugin was employed to pinpoint 14 genes (Cyba, Nfkbia, Fos, Mpo, Il6, Il1b, Sele, Vcam1, F2, Tlr4, Alb, Egr1, Smad3, and Ptgs2) forming a primary cluster, potentially representing a crucial regulatory network for berberine in treating allergic rhinitis." (PMID 38796469, 2024).
amyloid (1 paper, 2024). "Further, higher blood SMAD3 levels associated with less amyloid and cortical atrophy on antemortem imaging." (PMID 38902234, 2024). "In contrast, blocking of Smad3 signaling in peripheral macrophages of mouse models of amyloidosis reduced brain Aβ in both parenchyma and blood vessels via enhanced phagocytosis of Aβ, also reducing inflammation." (PMID 38902234, 2024).
angina pectoris (1 paper, 2014). The symptom of paroxysmal pain consequent to MYOCARDIAL ISCHEMIA usually of distinctive character, location and radiation. "However, SMAD3 levels were not significantly different among AMI, SAP, and UAP subgroups, suggesting that TGF-β1 may regulate the progression from angina pectoris to AMI." (PMID 24533640, 2014).
aortic valve calcification (1 paper, 2022). "Haploinsufficiency of Smad3 has been observed to be more potent in inhibiting aortic valve calcification compared to Tgfb1 ligand inhibition." (PMID 35928937, 2022).
Arrhythmia (1 paper, 2020). Any cardiac rhythm other than the normal sinus rhythm. "Furthermore, patchy fibrosis formation was reduced, potentially via inhibition of pro‐fibrotic TGF‐β/SMAD3 signalling, which related to a better global contractile performance and a slightly depressed incidence of arrhythmias." (PMID 32573944, 2020).